PSAT1 (phosphoserine aminotransferase 1)
Diseases named in the same sentence as PSAT1 in open-access papers (continued):
Sharing a sentence is not in itself a finding about the gene and the disease.
tumor (continued). "EBV miRNAs attack host mRNAs and some target carcinogenesis genes. miR-BART19-3p targets WIF1, a gene important in CRC. miR-BART1 targets PSAT1, a gene promoting the replication and proliferation of tumor cells." (PMID 35174040, 2022). "PSAT1 expression levels can influence the immune activity of tumor microenvironments, according to these results." (PMID 36061202, 2022). "miR-BART19-3p (miRNAs) is shown to attack WIF1 (host mRNAs), which is an important colon cancer gene, while miR-BART1 (miRNAs) attacks PSAT1 (host mRNAs), a tumor cell promoting gene." (PMID 35174040, 2022). "For instance, PSAT1 is highly expressed in ovarian cancer and is a candidate subtype-specific biomarker suggesting that the tumor is most likely a clear cell carcinoma." (PMID 36699468, 2022). "First, we used TIMER2 to compare the mRNA expression profiles and the expression level of PSAT1 in each type of tumor and their corresponding normal tissue." (PMID 36105075, 2022). "Their results describe for the first time the relationship between PERK signaling and PSAT1 mediated serine metabolism, and also suggest that PSAT1 is involved in the regulation of tumor immune microenvironment." (PMID 36105075, 2022). "Phosphoserine aminotransferase 1 (PSAT1) is involved in serine synthesis that functions as an oncogene during tumor progression and metastasis." (PMID 34593006, 2021). "Phosphoserine aminotransferase 1 (PSAT1) participates in cellular serine synthesis and has been observed to be elevated in different tumor types." (PMID 34439090, 2021). "Together these data suggest that lncRNA MEG8 contributes to tumor growth of NSCLC via the miR-15a-5p-miR-15b-5p/PSAT1 axis in vivo." (PMID 33526036, 2021). "Immunohistochemistry analysis of these tumours revealed that feeding mice with a -SG diet led to a clear induction of PSAT1 – and to a lesser extent PHGDH – in tumours, indicating the induction of an ATF-4 response in vivo." (PMID 33446657, 2021). "This indicates that both IKKε and PSAT1 are defining features in order to identify tumours where the pathway is actively promoting proliferation." (PMID 32783398, 2020). "Our stratification is also in agreement with previous studies, where strong correlation between PSAT1 expression and tumour proliferation has been found in ER− tumours." (PMID 32783398, 2020). "Our results confirmed that overexpression of the PSAT1 gene correlates with IDH1 mutations, a lower tumor grade, and a better outcome in LGGs in the CGGA dataset." (PMID 31861486, 2019). "As expected, overexpression of WT Nf1 in KPΔNF1 cells downregulates Fak1, downregulates its target genes Psat1, Areg, and Peg10, retards tumor growth, and rescues cytotoxicity induced by CB‐839 or AOA." (PMID 31036704, 2019). "Higher tumor grade and pN stage and low PSAT1 methylation levels categorized by P75significantly associated with worse disease-free survival (DFS) in Cox regression univariable analysis." (PMID 30405052, 2018). "Statistical analyses using IHC results revealed that PSAT1 was positively correlated with tumor size (P = 0.024), TNM stage (P = 0.026) and Ki67 status (P < 0.028)." (PMID 29216929, 2017). "As expected, the silencing of PSAT1 significantly suppressed HCC70 tumor growth in mice compared with the control group." (PMID 29216929, 2017). "Kaplan-Meier curves showed that patients whose tumors expressed high levels of PSAT1 suffered from faster tumor progression when compared to the PSAT1 low group (HR = 1.68; 95% CI: 1.20 to 2.36; Log-rank P = 0.003)." (PMID 28522855, 2017). "It is worthy to note that our current study of PSAT1 focused on GSK-3β, through which PSAT1 eventually enhanced the proliferation and metastasis of tumor cells." (PMID 29216929, 2017). "Immunodeficient BALB/c mice carrying HCC70 and HCC70-KD1 tumor cells were used to ascertain the role of PSAT1 in the tumorigenesis of ER-negative breast cancer in vivo." (PMID 29216929, 2017).
tumor (continued). "Statistical analysis of these results showed that PSAT1 up-regulation was correlated with tumor development and poor prognosis." (PMID 29216929, 2017). "Instead, the production of α-KG by utilization of glutamine coupled to the conversion of phosphorus-hydroxypyruvate to phosphoserine by PSAT1 was thought to be critical for tumor growth." (PMID 24318446, 2013). "We find that the genes coding for the enzymes in the novel ATP-producing pathway are induced following Myc induction, and all, but two (Psat1 and Psph), return to their control levels upon Myc downregulation-induced tumor regression." (PMID 22073143, 2011). "We first observed that PSAT1 was overexpressed in tumor samples from CRC patients, and that its level of overexpression after chemotherapy is correlated with poor regression of the tumour metastases." (PMID 18221502, 2008). "This inverse correlation between clinical progression and the PSAT1 ratio in tumor specimens was obtained using both RNA quantification methods, Affymetrix microarrays (data not shown) and RT-Q-PCR." (PMID 18221502, 2008). "For patients showing mild tumor regression (patients 2 and 3), the PSAT1 expression ratio increased, and this increase was greater when tumor regression was poor." (PMID 18221502, 2008). "When ADH1C overexpressed, suppresses the expression of Phosphoglycerate Dehydrogenase (PHGDH) and Phosphoserine Aminotransferase 1 (PSAT1), two key enzymes in the serine biosynthetic pathway, leading to lower intracellular serine levels and reduced tumor growth." (PMID 40951358, 2025). "In this study, we explored whether PSAT1 was overexpressed in ER-negative breast cancer and was related to tumor metastasis." (PMID 39199378, 2024). "Moreover, the suppression of PHGDH or PSAT1 significantly decreased the conversion of glutamate to αKG and decreased the cellular αKG pool in protumorigenic macrophages and in the serum of tumor-bearing mice." (PMID 38409249, 2024). "Taken together, we found that PSAT1 may be of particular interest in tumors harboring p5372P to target metabolic reprogramming for preventing tumor progression in clinical practice." (PMID 36788227, 2023). "Furthermore, single-sample gene set enrichment analysis was performed to detect the relationship between PSAT1 and tumor immune infiltration." (PMID 36906716, 2023). "On account of this, we speculate that PSAT1 is essential for tumor cells to survive metabolic stresses." (PMID 36788227, 2023). "UCSC database was used to analyze PSAT1 mRNA expression levels in tumor and normal tissue samples." (PMID 36061202, 2022). "In conclusion, these results demonstrate that PSAT1 plays a significant role in the recruitment and the modulation of tumor immune infiltrating cells and may ultimately have an impact on patients’ survival." (PMID 36105075, 2022). "This suggests that we need to dynamically observe the expression of PSAT1 in different stages of the same tumor and PSAT1 may have different roles in the progression of the tumor." (PMID 36105075, 2022). "These cells are not able to upregulate crucial genes from the serine biosynthesis pathway (SBP), such as phosphoglycerate dehydrogenase (PHGDH) and phosphoserine aminotransferase 1 (PSAT1), making them dependent on serine released by tumour-infiltrating nerves to the microenvironment." (PMID 34588983, 2021). "LncRNA MEG8 contributes to tumor growth of NSCLC via the miR-15a/b-5p/PSAT1 axis in vivo." (PMID 33526036, 2021). "The in vivo tumor volume and weight of BT-549 cells was significantly increased from 218.3 ± 40.28 mm3 to 877.0 ± 81.04 mm3 (p < 0.0001) and from 0.2000 ± 0.03651 g to 0.7833 ± 0.07032 g (p < 0.0001) respectively, when PSAT1 was overexpressed." (PMID 29216929, 2017). "Taken together, these data indicate that PSAT1 might be related not only to differential cell metabolism reprogramming, but also to immune cell signaling and lymphocyte tumor infiltration." (PMID 28522855, 2017).
tumor (continued). "In particular, it is possible that the overexpression of glycogen phosphorylase may liberate carbon units to be shunted from glycolysis into the serine biosynthesis pathway through PSAT1, as well as into the Golgi body for glycosylation in tumor cells." (PMID 25961905, 2015). "Following our analysis of PSAT1, we reasoned that a particularly interesting set of genes were those showing a higher degree of co-expression (as quantified by the magnitude of the Spearman correlation coefficient) in tumor samples relative to normal samples." (PMID 25961905, 2015). "For the patient showing the best tumor regression (patient 4), the PSAT1 ratio was very low." (PMID 18221502, 2008). "To determine whether the high PSAT1 mRNA levels is associated with clinical response, we explored the correlation between PSAT1 expression levels and tumor regression after chemotherapy." (PMID 18221502, 2008). "Furthermore, in esophageal squamous cell carcinoma and lung adenocarcinoma, PSAT1 silencing not only inhibits tumor growth but also acts synergistically with serine deprivation or erlotinib treatment, respectively, to overcome drug resistance in vitro and in vivo." (PMID 41415540, 2025). "Moreover, downregulating the rate-limiting enzymes of serine/glycine metabolism, such as phosphoserine phosphatase (PSPH) and phosphoserine aminotransferase 1 (PSAT1), may disrupt the pro-tumor effects mediated by serine/glycine metabolism." (PMID 40265021, 2025). "Interestingly, the function of PSAT1 in SHFSCs appears to parallel its role in tumor biology." (PMID 40234836, 2025). "PSAT1 is one of the key enzymes of the serine synthesis pathway and is thought to play an important role in the regulation of gene expression, DNA repair, cell proliferation, and metastasis in tumors, in addition to its role in the metabolic process of tumor cells." (PMID 39199378, 2024). "Notably, tumor growth suppression and the associated recruitment of mature DCs as well as CD8+ and CD4+ T cells caused by exogenous serine restriction in PSAT1-defective CT26 lesions could also be abrogated by the shRNA-mediated depletion of STING." (PMID 39206097, 2024). "Moreover, AOA had no obvious effect on the colony formation capacity of cells when PSAT1 was knocked down, indicating that the anti-tumor effect of AOA may be dependent on PSAT1." (PMID 36788227, 2023). "Therefore, high PSAT1 expression is essential for regorafenib to kill tumor cells." (PMID 36699468, 2022). "Importantly, PSAT1 overexpression was also sufficient to partially rescue the inhibition of MCF7 xenograft growth caused by dietary S/G starvation, demonstrating that at least part of the effect of S/G starvation is tumor cell intrinsic." (PMID 35045283, 2022). "The oncogenic function of PSAT1 has been investigated in many tumor types and has been found to play a role in the proliferation, migration, and chemo-resistance yet it remains elusive whether PSAT1 may contribute to the cellular response to specific oncogenic signaling, particularly EGFR." (PMID 34439090, 2021). "PSAT1 expression was significantly associated to shorter TTP both in univariate (HR = 1.77; 95% CI: 1.77 to 3.03; P = 0.037) and multivariate analyses (HR = 1.63; 95% CI: 1.02 to 1.59; P = 0.039) independent of traditional predictive factors (DFI, dominant site of relapse and tumor differentiation)." (PMID 28522855, 2017). "Therefore, we hypothesize that high expression of PSAT1 may be involved in tumor cell proliferation and may play an important role in ER-negative breast cancer development." (PMID 29216929, 2017). "Besides apoptosis, it appears that mitotic catastrophe, autophagy, and necrosis can participate in tumor cell death, indicating that PSAT1 may play an inhibitory role in one of these biological processes." (PMID 18221502, 2008). "The results showed that PSAT1 and PSPH were consistently upregulated in tumour tissues in five GEO datasets, while PHGDH, SLC1A4 and SLC38A5 were upregulated in four datasets." (PMID 40660426, 2025).
tumor (continued). "To further substantiate the influence of PSAT1 on EMT and its pivotal role in tumor metastasis, we introduced si-PSAT1 into HCT116 and SW480 cells." (PMID 38706897, 2024). "In addition, PSAT1 activation might protect tumor cells from oxidative damage by GSH production." (PMID 39407268, 2024). "Phosphoserine aminotransferase 1 (PSAT1), one of the key enzymes in the SSP, catalyzes the conversion of 3-phosphohydroxy-pyruvate to 3-phosphoserine and plays an important role in tumor development." (PMID 39199378, 2024). "Therefore, we inferred that PSAT1 might be a tumor suppressor gene." (PMID 38706897, 2024). "Our research has unveiled a notable down-regulation of PSAT1 in both CRC cell lines and tumor specimens obtained from CRC patients." (PMID 38706897, 2024). "In summary, PSAT-IQGAP1-STAT3 is upregulated in erlotinib-resistant cells, and PSAT1 promotes tumor metastasis and EGFR inhibitor resistance." (PMID 37381723, 2023). "PSAT1 protein expression was much higher in UCEC than in normal tissues, as demonstrated by the Clinical Proteomic Tumor Analysis Consortium (CPTAC) database." (PMID 36906716, 2023). "The expression of PSPH and SHMT2 was significantly higher in tumour tissues, whereas PHGDH and PSAT1 were reduced." (PMID 36110969, 2022). "To examine the ATF-4 response, we measured the expression of the two ATF-4 targets, PHGDH and PSAT1, in DLD-1 tumours." (PMID 33446657, 2021). "This analysis indicated that both IKBKE and PSAT1, similarly to PHGDH and PSPH, are significantly upregulated in an ER‐negative Pam50:basal subpopulation of tumours, with the highest proliferation index." (PMID 32783398, 2020). "Meanwhile, RT-qPCR assays revealed that ALDH6A1, FBP1, HAO2 and PSAT1 were markedly under-expressed in tumor tissues in exceeding 60% cases, and that TYMP, HK3, P4HA3, IL4I1, CYP26A1 and CPT1B were over-expressed in tumor tissues in exceeding 70% cases." (PMID 32737333, 2020). "Between the two groups, tumour tissue had significantly upregulated G6PD (p < 0.0001), unaltered 6PGD, and PHGDH and PSAT1 were significantly downregulated (p < 0.0001), versus the non-tumour tissue." (PMID 33028928, 2020). "The tumor promoters BASP1, GPC1, PSAT1 and SH3BGRL are reported to be typically expressed in macrophages by the Expression Atlas." (PMID 32466393, 2020). "BRAFV600E mutant cells have higher PHGDH, PSAT1, PSPH, tumor SHMT1, and interstitial SHMT1 and GLDC expression than non-mutant cells." (PMID 31423225, 2019). "Mechanisms whereby tumours sustained HT under CD44-knockdown conditions include upregulation of PHGDH, PSAT1 and PSPH that drove glycolysis-dependent activation of serine/glycine-cleavage systems to provide one-methyl group for HT synthesis." (PMID 29674746, 2018). "Validation of selected mRNAs was performed on the same patients cohort by RT-qPCR and, according to the expression profiling results, we evidenced the up-regulation of Golm-1, Psat-1 and CDH2 in tumor tissues compared to normal samples." (PMID 28486946, 2017). "In our study, knockdown of HNRNPM in HCT116 xenograft models led to increased PSAT1 expression, yet had no observable impact on tumor growth." (PMID 40784984, 2025). "We observed that the PSAT1 expression was up-regulated in all tumor tissues compared with matched noncancerous tissues, and that the expression was higher in late-stage tumor tissues." (PMID 38614981, 2024). "We further detected the protein expression levels of PSAT1 in 20 pairs of tumor and adjacent noncancerous tissues, including tissues from 10 pairs from early-stage and 10 pairs from late-stage cases." (PMID 38614981, 2024). "As previously noted, NSCLC patient tumor samples showed higher expression of the different enzymes of the de novo ser/gly synthesis pathway, i.e. PHGDH, PSAT1, PSPH and SHMT2, compared to the adjacent normal lung tissue, which hardly showed any expression of ser/gly pathway enzymes." (PMID 38160212, 2024).
tumor (continued). "Interestingly, the expression of these genes increases with tumor staging of NSCLC (p < 0.0001 for PSAT1, PSPH and SHMT2)." (PMID 38160212, 2024). "PSAT1 expression levels in UCEC were employed using the paired sample t-test, Wilcoxon rank-sum test, the Clinical Proteomic Tumor Analysis Consortium database, and the Human Protein Atlas database, while survival curves were constructed using the Kaplan–Meier plotter." (PMID 36906716, 2023). "In serine/glycine metabolism, tumor cells synthesize and utilize serine/glycine by a phosphoglycerate dehydrogenase (PHGDH)/phosphoserine aminotransferase 1 (PSAT1)/phosphoserine phosphatase (PSPH)/hydroxymethyltransferase (SHMT)-mediated continuous enzymatic reaction." (PMID 36778122, 2023). "Additionally, a remarkable correlation was found between PSAT1 expression and TMB in LUAD, and the expression of PSAT1 was negatively correlated with the Tumor Immune Dysfunction and Exclusion (TIDE) value, suggesting a good effect of immunotherapy." (PMID 36105075, 2022). "Interestingly, the expression level of PSAT1 in LGG has nothing to do with tumor purity, which indicates that it has the same expression in tumor cells and tumor microenvironment." (PMID 36105075, 2022). "To assess the clinical relevance of targeting the SSP in CRC for radiosensitizing purposes, we first examined mRNA levels of PHGDH, PSAT1 and PSPH in patient-derived data from normal tissues (TCGA Target GTEx) and CRC tumor tissues (TCGA COAD study) using the online Xena Explorer tool." (PMID 36291844, 2022). "However, high expression of PHGDH, PSAT1, and PSPH is ubiquitous in tumor cells, which activates endogenous serine metabolism and thus weakens the effect of serine starvation on tumor treatment." (PMID 36699468, 2022). "A-485 and B029-2 are two selective and highly potent p300 inhibitors that suppress tumor cell metabolism and tumor progression by targeting p300/CBP and reducing the levels of key metabolic enzyme genes, such as PSPH, PSAT1 promoter region H3K18Ac, and H3K27Ac." (PMID 36699468, 2022). "Unlike PHGDH, PSAT1 overexpression has not been found in TNBC tumor cells, and PSAT1 upregulation is generally presumed to result from responses to oncogenic signals." (PMID 32296646, 2020). "In serine synthesis-independent TNBC cells, PSAT1 suppression blocks invasion without negatively affecting primary tumor growth." (PMID 32296646, 2020). "Expression of PHGDH, PSAT1, PSPH and tumor SHMT1 is higher in PDTC and PTC, but lower in MTC." (PMID 31423225, 2019). "Because nearly all of the strongest signals came from loss of positive correlation in normal samples, we further identified those genes with which PSAT1 was more strongly co-expressed in tumor samples than in normal samples." (PMID 25961905, 2015). "In parallel, upon RUNX2 knockdown, we have observed a predominant and strong downregulation of gene nodes known to be implicated in EOC tumorigenesis (PTGS1/COX1, FGF2, IL1A, Sapk, C/ebp, SELE, UBQLN1, PSAT1, ALDH1A1, GDF15, MTHFD2), including EOC tumor invasion/metastasis (MMP1, MMP13, Creb);." (PMID 24124450, 2013). "Interestingly, in tumor tissues from mice models of hydrodynamic tail-vein injection induced by TRIM71, oncofetal-like ecological characteristics are activated, along with the upregulation of key serine/glycine regulatory genes Psph and Psat1." (PMID 39267787, 2024). "Our finding revealed a non-enzymatic role of PSAT1, in which PSAT1 might be essential for metabolic rerouting during tumor cell metastasis, and targeting PSAT1 may hold the potential to benefit tumor treatment by inhibiting mitochondrial metabolism." (PMID 36788227, 2023).